INS (insulin)
Diseases named in the same sentence as INS in open-access papers (continued):
Sharing a sentence is not in itself a finding about the gene and the disease.
diabetes (continued). "In patients with diabetes, the value of HOMA-IR and insulin level for evaluating insulin sensitivity is still controversial." (PMID 35627914, 2022). "Only two participants reported receiving diabetes treatment among the PLHIV, including insulin and an oral agent." (PMID 36451447, 2022). "The observation of impaired beta cell function in young lean Asian Indians persisted after adjusting for sex, family history of diabetes, HDL-C and insulin sensitivity." (PMID 35247066, 2022). "As such, BAT has the potential to not only be therapeutic but also a preventive mediator in lifestyle-related diseases, particularly diabetes mellitus, due to BAT activation improving whole-body glucose homeostasis and insulin sensitivity in humans." (PMID 36017333, 2022). "Diabetes mellitus (DM) is a metabolic disease associated with disordered carbohydrate metabolism and decreased or absence of insulin sensitivity and production." (PMID 35675226, 2022). "Indeed, the observed differences in baseline characteristics between the groups (diabetes duration, HbA1c, fasting glucose, body mass index, different use of medications) may point to more severe insulin secretory defect in the ICT group compared to the IDegLira group." (PMID 36104712, 2022). "Type 1 diabetes mellitus (T1DM) is an autoimmune disease, which is characterized by decreased insulin secretion from the pancreas." (PMID 35518934, 2022). "Utilise lived experiences to advocate for insulin therapy amongst PLWD and promote better diabetes care." (PMID 35924623, 2022). "Metformin (MET) is the most commonly used drug to treat non-insulin dependent diabetes mellitus (type 2 diabetes, DM2), and the most thoroughly investigated insulin-lowering agent to treat PCOS." (PMID 36614868, 2022). "Whereas, in the later stage of diabetes (>5 years), patients with SIRD and MARD need additional insulin therapy, only the MOD population can be treated with non-insulin drugs to meet glycemic needs." (PMID 36457559, 2022). "DM is typically divided into types 1 and 2, with people predominantly suffering from type 2 diabetes mellitus (T2DM), which mainly involves the inoperability of produced insulin at the site of action." (PMID 36355487, 2022). "For instance, in obesity and type 2 diabetes, M2-like macrophages keep the adipocytes responding to insulin, and Th2 CD4 cells seem to protect from insulin resistance in obesity models, whereas Th1 CD4 cells drive diabetes." (PMID 35903540, 2022). "Two out of these three participants were still in remission phase, with a diabetes duration of 3 months, and used DEX and insulin pens." (PMID 36553394, 2022). "TXNIP is upregulated in β-cells during diabetes and has been shown to induce miR-204 by the inhibition of STAT3 phosphorylation, which in turn directly inhibits MAFA and insulin expression." (PMID 35562869, 2022). "Insulin is designated to be the most standard therapy for pregnant women having TIDM and diabetes during pregnancy whose hyperglycemic conditions sustain uncontrolled after alterations in food plan and lifestyle." (PMID 35723344, 2022). "Notably, a previous study indicated that when hepatic insulin signaling is impaired in type 2 diabetes, its ability to induce a glycogen decomposition and gluconeogenesis is impaired, leading to an excessive glucose production and further fasting hyperglycemia in diabetes." (PMID 36430435, 2022). "In Type 2 Diabetes Mellitus (T2DM) animal models, FMT can improve HOMA-IR and insulin sensitivity and repair damaged islets, providing a potential strategy for the treatment of T2DM." (PMID 35528013, 2022). "Specifically, they used CGM readings, glucose meter measurements, insulin dosage, ECG, HRV, diabetes duration, and hemoglobin A1c levels and achieved an accuracy of 99% and a sensitivity of 79%." (PMID 35862181, 2022).
diabetes (continued). "Previous reports showed that GCK methylation is a more suitable marker than INS methylation for the detection of β-cell death in T1DM and therefore can present an early diabetes biomarker." (PMID 35207316, 2022). "Age, SBP, diabetes duration, current smoking, ALT, GGT, CysC and HbA1c increased with ascending serum ADA quartile, whereas eGFR and insulin sensitivity index (IS-CP) decreased." (PMID 36267565, 2022). "Furthermore, aberrant insulin secretion rhythm could be improved after combined intervention with key receptors and kinases, which could provide a potential therapeutic method for diabetes mellitus in the future." (PMID 35758323, 2022). "This bidirectional relationship between SARS-CoV-2 and diabetes, where, on the one hand, diabetes represents a risk factor for more severe SARS-CoV-2 infection outcomes and on the other hand, SARS-CoV-2 has direct effects on the pancreas, may lead to reduced insulin release." (PMID 35256883, 2022). "Promote better diabetes care for PLWD, reduce referrals for insulin initiation and improve patient outcomes." (PMID 35924623, 2022). "Several studies have assessed the correlation between additional variables (i.e., age, gender, type of DM, glycemic control, BMI, eGFR, comorbidities such as hypertension, type of diabetes management, insulin therapy) and antibody response in patients with DM vs. patient without DM." (PMID 36105809, 2022). "PPAR signaling pathway: direct action of peroxisome proliferator-activated receptors (PPAR)-γ often results in improved insulin sensitivity, which also acts as major drug target for thiazolidinedione (TZD) in the treatment of diabetes mellitus." (PMID 35207564, 2022). "While T1DM is an autoimmune disease that leads to destruction of the insulin-producing pancreatic beta cells and frequently occurs during childhood or young adulthood, T2DM accounts for up to 90% of diabetes and this number is expected to increase over time." (PMID 35672565, 2022). "Therefore, although the treatment effects were numerically small, the improvement in HbA1c and the reduced need to initiate insulin treatment that was observed with sacubitril/valsartan in this secondary analysis may benefit people with heart failure and diabetes." (PMID 35717169, 2022). "Type 2 diabetes mellitus (T2DM) is a chronic metabolic endocrine disease characterized by insulin resistance and insufficient insulin secretion." (PMID 35965680, 2022). "Clearly, these studies demonstrated that MALAT1 played important roles in regulating hepatic insulin sensitivity, and inhibiting MALAT1 expression represents a potential therapeutic strategy for the treatment of IR and diabetes." (PMID 36555704, 2022). "Simulated diabetes augmented and reduced the protein levels of PPP2R2B and YWHAB in BCAEC, respectively, which suggest impaired insulin signaling in our model." (PMID 35835939, 2022). "Diabetes mellitus (DM) is a group of pathological alterations characterized by hyperglycemia in the absence of treatment, which may come from insulin resistance, from inadequate insulin secretion or from disturbances in the metabolism of carbohydrates, fats, and proteins." (PMID 34961280, 2021). "Among the various characteristics of diabetes, the impact of higher FGV was more distinct in patients with a long duration of diabetes and the prescription of metformin, sulfonylurea, AGI, and insulin." (PMID 34945244, 2021). "Ga = gastrin, Glu = glucagon, In = insulin, PP = polypeptide, SS = somatostatin, VIP = vasoactive intestinal peptide, DM = diabetes mellitus, RFA = radiofrequency ablation." (PMID 34118524, 2021). "In several studies on potential drugs improving insulin sensitivity in T2DM, vaspin, like other adipokines such as omentin, visfatin, or adiponectin, is considered a biomarker of diabetes and a potential indicator of drug efficiency." (PMID 34359881, 2021).
diabetes (continued). "Although the evidence of a correlation between diabetes and neurodegenerative pathology in LOAD is mixed, some human postmortem findings suggest a link between brain insulin tolerance and increased LOAD pathology, including increased Aβ deposition." (PMID 34577590, 2021). "Sulfonylurea drugs, commonlyused in type 2 diabetes mellitus treatment, bind to the octamer KATPchannels composed of four pore-forming Kir6.2 and four SUR1 subunitsand increase the probability of insulin release." (PMID 34825567, 2021). "It is involved in glucose-stimulated insulin secretion (GSIS) impairment and arsenic-induced pancreatic damage in the pathogenesis of diabetes." (PMID 34258295, 2021). "Parents expected SAPT to simplify diabetes management and to enable a “normal” life for their child, while adolescents expected that CGM and insulin pump data sharing would reduce parental anxiety at night." (PMID 33528374, 2021). "With regards to diabetes, it is now well established that chronic administration of GLP-1R mimetics not only enhances insulin secretion but also positively influences overall islet function, restoring normal morphology in even severe models of diabetes." (PMID 34093449, 2021). "Glucose phosphorylation by GCK is related to insulin secretion; therefore, GCK gene dysfunction or aberration leads to decreased glucose-mediated insulin release and glucose intolerance or diabetes." (PMID 34203830, 2021). "The ARD study stratifies individuals based on three types of diabetes treatment: insulin only, orally administered drug (OAD) only, and insulin + OAD treatment." (PMID 34286296, 2021). "Post-hoc analysis identified that blood insulin was significantly reduced in T2D (p = 0.03) and CON (p = 0.01) diabetes following surgery." (PMID 34690929, 2021). "In the period when SGLT2i were available (2014q1–2019q4), there were 8,312,293 total reports, 62,098 of which contained at least one SGLT2i as suspect or concomitant and 642,031 contained at least another diabetes drug of the ATC class A10, including insulin." (PMID 33573667, 2021). "Changes in the insulin signaling pathway of PI3K/ATK are closely related to decrease of insulin sensitivity and the development of diabetes." (PMID 34026064, 2021). "This is in contrast to studies in other models of diabetes where HIF-PHIs improved glucose tolerance in mice fed a high fat diet and treated with FG-4497 for 4 weeks, and ameliorated insulin sensitivity in BTBR ob/ob mice treated for 18 weeks with enarodustat." (PMID 34339435, 2021). "However, a shallow frequency was noted on diabetes as a condition of insufficient insulin production, hypoglycemia symptoms, healthy blood sugar level, the importance of hemoglobin A1C, and correct foot care, as well as the relationship between physical activity, heart failure, and diabetes." (PMID 33579243, 2021). "Collectively, these results indicate that diabetes induces DPP4 expression and suppress insulin-induced Akt activation in the liver, and the injection of non-diabetic plasma into the adipose tissue of diabetic animals reverses those effects." (PMID 34043673, 2021). "Diabetes mellitus (DM) is a metabolic disease that has multiple etiologies and is characterized by hyperglycemia and the abnormal metabolism of glucose, fat, and protein due to insufficient insulin secretion and/or insulin resistance." (PMID 34362349, 2021). "Type 2 diabetes mellitus (T2DM), which is present in most individuals with diabetes, is characterized by insulin hyposecretion and insulin resistance." (PMID 34603199, 2021). "Luteolin has been shown to improve blood glucose, glycosylation, insulin, and HOMR-IR levels in diabetic model mice, with positive effects against diabetes and its complications." (PMID 34159207, 2021).
diabetes (continued). "Since ketone bodies participate in body metabolic rewiring in fasting and diabetes, two conditions associated with muscle wasting, HMB, by attenuating histone Kbhb and the associated catabolic genetic response, may help to maintain muscle mass in conditions of low insulin signaling." (PMID 34436453, 2021). "Since insulin pumps and CGM data can be uploaded from home and automatically accessed anywhere by an HCP, it is feasible for practically anyone to start a diabetes technology to manage their disease." (PMID 32678672, 2021). "Autophagy is a potential mechanism through which arsenic exposure induces adverse health outcomes including type 2 diabetes mellitus (T2DM); hepatic autophagy impacts cellular metabolism and affects glucagon and insulin levels." (PMID 34243768, 2021). "Many mechanisms are considered to be involved in the link between depression and diabetes, including HPA axis dysregulation, immune and inflammatory mechanisms, brain insulin resistance, circadian rhythm dysregulation, shared genetic factors and more." (PMID 34912246, 2021). "Regulating insulin and leptin levels using a protein tyrosine phosphatase 1B (PTP1B) inhibitor is an attractive strategy to treat diabetes and obesity." (PMID 34299651, 2021). "Background and Objectives: Insulin treatment may be initially required to stabilize patients presenting with metabolic crisis at type 1 and 2 diabetes mellitus (DM) onset." (PMID 34577825, 2021). "Only after a couple of weeks of talking to the diabetes educator and the doctor I understood how to maintain my BGL, but by then I was already on insulin”." (PMID 34243754, 2021). "Type 2 diabetes mellitus (T2DM) is a metabolic disorder with insulin resistance (IR) and impaired insulin secretion." (PMID 34938192, 2021). "The first two are carbohydrate degrading enzymes; thus, they can retard the absorption of glucose into the bloodstream, thereby controlling diabetes, while DPP-IV inhibition promotes the release of insulin, resulting in low blood glucose levels." (PMID 33924574, 2021). "Further confirmation of diabetes was obtained on OGTT, ITT, and blood insulin measurements to establish both glucose intolerance and insulin resistance." (PMID 34355034, 2021). "The study explored FHL levels and numeracy skills in an insulin-treated T2DM patient population, and their impact on diabetes self-care activities." (PMID 33561956, 2021). "Overnutrition is a major forerunner of type 2 diabetes mellitus (T2DM), which can both enhance secretion of insulin and attenuate its metabolic actions on peripheral tissues including liver, skeletal muscle, and adipose tissue." (PMID 33817571, 2021). "Diabetes mellitus (DM) is a common metabolic disease and is divided into type I and type II diabetes mellitus based on the dependence on the intake of exogenous insulin by DM patients, among which type II diabetes mellitus (T2DM) occupies approximately 90% in the total population." (PMID 34266350, 2021). "Namely, in Akita mice (which develop diabetes spontaneously) the knockout of RNF213 lowers glucose tolerance by 20% and leads to increased insulin contents in pancreases (by 150%) compared to wild type animals." (PMID 33472578, 2021). "A 4-week subcutaneous injection of estradiol to ovariectomized female mice with STZ-induced type 1 diabetes significantly suppressed blood GLU level and increased plasma insulin, suggesting protective effects of estradiol against STZ-induced diabetes." (PMID 34959884, 2021). "Similar to CVDs, the dispensing rates of diabetes medicines, including insulin dispensing rates, were significantly higher among males than females; however, the WHO has reported a higher prevalence of diabetes among females in Syria than males." (PMID 34645430, 2021). "Diabetes induction increased body weight (BW) and FBG, and decreased insulin compared to the ND rats’ groups (p < 0.001)." (PMID 34039404, 2021).
diabetes (continued). "In diabetics, PTP1B expression, is increased, and insulin signal is attenuated resulting from increased serine/threonine phosphorylation and decreased tyrosine phosphorylation of the insulin receptor." (PMID 35008779, 2021). "Pancreatic islet β-cell dysfunction is characterized by defective glucose-stimulated insulin secretion (GSIS) and is a predominant component of the pathophysiology of diabetes." (PMID 33606677, 2021). "It is important to mention that hyperglycemia resulting from streptozotocin-induced diabetes increases the activity of the HPA axis, while normalizing glucose with either insulin or phloridzin corrects this hyperactivity." (PMID 34681832, 2021). "Type 1 diabetes mellitus (T1DM) is an autoimmune disorder, where the insulin-producing pancreatic β-cells are destroyed, preventing the body from producing a sufficient level of insulin hormone to control normal blood glucose levels." (PMID 33747345, 2021). "Thus far, insulin administration remains the cornerstone of DM management, and earlier studies have shown that insulin therapy could dominate blood sugar and ameliorate bone regeneration of implants for diabetics." (PMID 33446235, 2021). "The reason for this may be that those with a higher BMI have less severe metabolic decompensation and hence easier and less difficult to control diabetes unlike those who are underweight and have absolute loss of insulin which results in catabolic state and significant weight loss." (PMID 33855206, 2021). "Open‐source algorithms for closed loop or automated insulin delivery (AID) predate commercial availability of such systems and have been developed by members of the diabetes community." (PMID 33931977, 2021). "In diabetes, the increase in inflammatory cytokines leads to dysregulation of IRS1 phosphorylation, which impairs insulin signal transduction in favor of ERK signaling pathways while blocking AKT activation." (PMID 34829877, 2021). "Glucagon-like peptide-1 (GLP-1) increases insulin secretion from pancreatic beta-cells and GLP-1 receptor (GLP-1R) agonists are widely used as treatment for type 2 diabetes mellitus." (PMID 33903116, 2021). "Type 2 diabetes mellitus (T2DM) is a chronic metabolic condition characterized by glucose clearance abnormalities and insufficient insulin response." (PMID 34501954, 2021). "Type 1 diabetes mellitus (T1DM) is attributed to pancreatic β cells destruction and insulin production insufficient." (PMID 34268308, 2021). "Metformin, which is widely prescribed for type 2 diabetes mellitus (T2DM) patients, regulates blood sugar by inhibiting hepatic gluconeogenesis and promoting insulin sensitivity to facilitate glucose uptake by cells." (PMID 34502359, 2021). "Diabetes mellitus (DM) is a chronic metabolic disease caused by the lack of insulin and impaired insulin secretion." (PMID 33440884, 2021). "Production of insulin autoantibodies (IAA) indicates spontaneous anti-insulin autoimmunity and IAA are frequently detected prior to diabetes onset in both humans and NOD mice." (PMID 33841427, 2021). "Type 2 diabetes mellitus (T2DM) is a multifactorial disease, mainly characterized by a decrease in insulin sensitivity and also by a defect in insulin secretion and chronic inflammation." (PMID 33520042, 2021). "Overall, 25% and 40% of patients with diabetes only and with both diabetes and CKD, respectively, were taking insulin." (PMID 33648518, 2021). "Diabetes mellitus (DM) is a group of metabolic diseases characterized by chronic hyperglycemia and impaired carbohydrates, lipids, and protein metabolism resulting from defects in insulin secretion, insulin action, or both." (PMID 33772019, 2021). "Pre-transplant diabetes is often ameliorated in CKD due to impaired clearance of insulin and many glucose lowering agents, despite the peripheral tissue insulin resistance." (PMID 34104484, 2021).